FAM90A1 (family with sequence similarity 90 member A1)
Synonyms: FLJ10408
Tractability: No criterion of Open Targets' tractability assessment is met for any kind of drug.
Gene: Protein-coding gene on chromosome 12 (8,221,260 to 8,227,621, reverse strand). Ensembl gene ENSG00000171847.
Subcellular location (Human Protein Atlas): Nucleoplasm; Nucleoli
Gene Ontology:
Molecular function: protein binding
Genetic constraint (gnomAD): Loss-of-function variants: 9 observed, 11.55 expected, observed/expected ratio (o/e) 0.78, 90% interval 0.47 to 1.36. The upper end of that interval is the gene's LOEUF score, 1.36, which puts it in group 5 of 6, group 1 being the genes least tolerant of losing a copy. Missense variants: 566 observed, 549.29 expected, observed/expected ratio (o/e) 1.03, 90% interval 0.96 to 1.11. Synonymous variants: 235 observed, 226.89 expected, observed/expected ratio (o/e) 1.04, 90% interval 0.93 to 1.15.
Homologues: Orthologues: chimpanzee FAM90A1 (96% identical), mouse Fam90a1b (29% identical), mouse Fam90a1a (26% identical), rat Fam90a1l1 (25% identical). Paralogues in human: FAM90A26 (94% identical), FAM90A3 (93% identical), FAM90A5 (93% identical), FAM90A15 (93% identical), FAM90A16 (93% identical), FAM90A17 (93% identical), FAM90A13 (92% identical), FAM90A14 (92% identical), FAM90A23 (92% identical), FAM90A9 (92% identical), FAM90A10 (92% identical), FAM90A11 (92% identical), and 9 more.
Diseases named in the same sentence as FAM90A1 in open-access papers:
FAM90A1 is named in the same sentence as 4 diseases in open-access papers, as found by Europe PMC text mining. Sharing a sentence is not in itself a finding about the gene and the disease. The quoted sentences say what the papers report.
B-cell lymphomas (1 paper, 2015). "FAM90A1, the fourth most significantly mutated gene among B-cell lymphomas (16%) belongs to a gene family with 25 members in the human genome, several resulting from a primate-specific gene duplication." (PMID 26377837, 2015).
endometrial cancer (1 paper, 2018). Primary or metastatic malignant neoplasm involving the endometrium (mucous membrane that lines the endometrial cavity). "FAM90A1 is an unfavorable prognostic marker in endometrial cancer." (PMID 30012096, 2018).
lymphoma (1 paper, 2015). A malignant (clonal) proliferation of B- lymphocytes or T- lymphocytes which involves the lymph nodes, bone marrow and/or extranodal sites. "Only seven genes (7%) were significantly (as determined by MuSiC analysis) mutated in both lymphoma immunophenotype groups, such as the proteasome subunit gene PSMA1, and the genes encoding the two uncharacterized proteins FAM90A1 and TBC1D26." (PMID 26377837, 2015).
tumor (4 papers, 2020 to 2026). "The DNA methylation and expression levels of FAM90A1 and ING2 are associated with tumour regrowth, and may serve as biomarkers for predicting the prognosis of patients with NFPA." (PMID 32015217, 2020). "These analyses identified several differentially methylated genes linked to invasiveness (e.g., PHYHD1, WNT4, STAT6, CDH1, CDH13), aggressive behaviour (e.g., AIP, PDCD1, LINE-1), and tumour regrowth (e.g., TERT, FAM90A1, ING2)." (PMID 41866138, 2026). "The progression-free analysis found that FAM90A1, ETS2, STAT6, MYT1L, ING2 and KCNK1 are related to tumour regrowth." (PMID 32015217, 2020). "FAM90A1 and ING2 was found to be independent prognostic factors of tumour regrowth with univariate Cox regression." (PMID 32015217, 2020). "Through prognostic analyses of clinical parameters and six genes, age, FAM90A1 and ING2 was found to be the indenpendent factors of tumour regrowth." (PMID 32015217, 2020). "Age, expression of FAM90A1 and ING2 are independent prognostic factors of tumour regrowth." (PMID 32015217, 2020). "The DNA methylation and expression levels of FAM90A1 (Family with Sequence Similarity 90 Member A1) and ING2 (Inhibitor of Growth Family Member 2) are associated with tumor regrowth in non-functioning PitNETs and may serve as biomarkers for predicting the prognosis in these cases." (PMID 40362297, 2025).